IL21 (interleukin 21)
Diseases named in the same sentence as IL21 in open-access papers (continued):
Sharing a sentence is not in itself a finding about the gene and the disease.
viral encephalitis (3 papers, 2016 to 2023). Encephalitis resulting from viral infection. "Our study on cell culture model is corroborated with above finding in which we reported decreased levels of IL-21 and FoxP3+ which suggests that FoxP3+ level was decreased due to decreased level of IL-21 suggesting IL-21 has a role in the homeostasis of Tregs in viral encephalitis." (PMID 36707891, 2023). "Translating these findings into routine clinical practice, IL-21 and IP10 may contribute to the diagnostic armamentarium in the investigation of encephalitis, possibly helping to differentiate AE from conditions presenting in a similar fashion where immunosuppression may be harmful." (PMID 32116981, 2019). "IL-4 CCL11, CCL17, CCL21), Th17 (IL-17A, GM-CSF), B cell molecules (BAFF, APRIL) and other cytokine/chemokines including IL-21, IL-1b, IL-12p40, CCL2 and IL-12p70 were detected in less than 50% of patients with encephalitis." (PMID 27575749, 2016). "We have demonstrated the CSF cytokines CXCL10/IP-10 and IL-21 are potential differentiators of AE from viral encephalitis, particularly when there is no CNS specific autoantibody detected." (PMID 32116981, 2019).
X-linked severe combined immunodeficiency (3 papers, 2019 to 2021). "X-linked severe combined immunodeficiency (X-SCID) is caused by mutations of IL2RG, the gene encoding the interleukin common gamma chain (IL-2Rγ or γc) of cytokine receptors for interleukin (IL)-2, IL-4, IL-7, IL-9, IL-15, and IL-21." (PMID 34248995, 2021). "The similarity of IL-21 to IL-2, IL-4, and IL-15, suggests the possibility that IL-21 might share an important receptor on the common cytokine receptor γ chain (γc), encoded by IL2RG, the gene found to be mutated in humans with X-linked severe combined immunodeficiency (XSCID)." (PMID 33924897, 2021).
acute pancreatitis (2 papers, 2023 to 2024). An acute inflammatory process that leads to necrosis of the pancreatic parenchyma. "Further research is necessary to determine the exact role of TFH cells and the impact of IL‐21 in acute pancreatitis, especially in light of IL‐21's potential therapeutic use in modulating the immune response to AP." (PMID 39023414, 2024). "However, additional studies are needed to elucidate the precise role of TFH cells and the impact of IL-21 in the context of acute pancreatitis, particularly in terms of the potential therapeutic use of IL-21 to regulate immune responses in AP." (PMID 37296616, 2023).
adenoma (2 papers, 2022 to 2025). A neoplasm arising from the epithelium. "Increased NK cell infiltration in the CR adenoma and carcinoma was also related to the over-expression of IL-21, which is known to enhance NK cell activity." (PMID 40149674, 2025). "Our data showed a stepwise increase in IL-21 mRNA expression, which began to increase at the adenoma stage and was maintained at a higher level at the CRC stage." (PMID 40149674, 2025). "The dynamics of IL-21 mRNA were recently examined along with the progression of the adenoma-carcinoma pathway." (PMID 35884974, 2022). "The levels of IL-21 were higher in adenomas and carcinomas than in controls." (PMID 35884974, 2022).
Autosomal dominant hyper-IgE syndrome (2 papers, 2016 to 2025). 2000 IU/ml), recurring staphylococcal skin abscesses, and recurrent pneumonia with formation of pneumatoceles. "A critical role for STAT3 in IL-21 signaling was also confirmed in patients with autosomal dominant hyper-IgE syndrome (AD-HIES), which is caused by loss-of-function mutations of STAT3." (PMID 26966515, 2016). "This regulatory balance is evident in patients with autosomal dominant hyper-IgE syndrome (AD-HIES, also known as Job syndrome), where STAT3 deficiency due to autosomal dominant mutations results in impaired STAT3 activation, altering cellular responses to IL-21." (PMID 40305224, 2025).
B cell deficiency (2 papers, 2016 to 2021). A broad classification of disorders where circulating numbers of B lymphocytes are decreased or ineffective. "There is evidence that IL21 participates in B cell activation and proliferation through its specific receptor (IL21R) and regulates germinal center and humoral immunity, while lack of IL-21 leads to memory B cell deficiency." (PMID 34383171, 2021).
Brain atrophy (2 papers, 2013 to 2022). Partial or complete wasting (loss) of brain tissue that was once present. "An increased frequency of IL-21 producing CD4+ T cells had been noted in AD and the extent of brain atrophy was highly correlated with increased IL-21 producing CD4+ T cells." (PMID 35648273, 2022). "Notably, the correlations between MRI parameters and BDNF secreting immune cells were lost in AD in whom, instead, brain atrophy was positively correlated with IL-21-producing CD4+ T cells." (PMID 24324435, 2013).
breast tumor (2 papers, 2016 to 2021). "Moreover, similar to HER2+ breast tumors, Il21 is not readily detected in B16 and NBL tumors from control or Cbx3/HP1γ-deficient mice." (PMID 34721405, 2021).
bullous pemphigoid (2 papers, 2013 to 2016). Bullous pemphigoid (BP) is the most common form of autoimmune bullous dermatosis. "Recently, IL-21 levels and Tfh cells were also found to be increased in the pemphigus-related blistering disease bullous pemphigoid." (PMID 26872212, 2016).
cholangitis (2 papers, 2017 to 2022). An acute or chronic inflammatory process affecting the biliary tract. "In p40−/−IL-2Rα−/− mice, deletion of IL-18 has no remarkable effect on disease progression, while deletion of IL-21 indicates that it is necessary for AMA production but independent of liver inflammation and cholangitis." (PMID 35300072, 2022).
cholesteatoma (2 papers, 2014 to 2021). A pathologic process characterized by the proliferation of keratinizing squamous epithelium resulting in the accumulation of keratin and cells in the middle ear and/or mastoid. "Our recent cytokine analyses revealed an up-regulation of the skin hyperplasia inducing IL-21 in cholesteatoma." (PMID 25093596, 2014).
Chronic colitis (2 papers, 2021). A chronic inflammatory disease of the large intestine (colon, cecum and rectum). "In the present study, significant increases in the production of IL-6, IL-12p70, IL-1β, TNF-α, IFN-γ, IL-21, and IL-17A and decreases in the production of IL-10 were observed in the chronic colitis group compared with the control group, and these changes were restored by NAM treatment." (PMID 33748287, 2021). "Regardless of whether there was anti-CD3/CD28 antibody stimulation, IFN-γ, IL-17A, and IL-21 were significantly decreased (P < 0.05), and IL-10 was significantly increased in the chronic colitis + Se-enriched L. acidophilus group compared with the chronic colitis group (P < 0.05)." (PMID 34532332, 2021). "The concentrations of IFN-γ, IL-21, and IL-17A were significantly lower, while the concentration of IL-10 was significantly higher, in the NAM+chronic colitis group than in the chronic colitis group." (PMID 33748287, 2021).
chronic gastritis (2 papers, 2017 to 2021). Inflammation of the stomach that is chronic in nature. "IL-21 could maintain pro-inflammatory T cell response to drive H. pylori infection-induced chronic gastritis." (PMID 34589088, 2021). "Moreover, IL-21 is highly produced in the gastric mucosa of H. pylori-infected patients and could maintain the pro-inflammatory T cell immune response to drive chronic gastritis during H. pylori infection." (PMID 34589088, 2021). "The expression of cytokines IL-23, IL-21, TNF-α, and IL-10 did not have a significant association with the severity of chronic gastritis in this study." (PMID 29391865, 2017). "Expression of serum cytokines (IL-17A, IL-21, IL-23, IL-10, and TNF-α) in H. pylori-infected patients was compared with healthy controls and correlated with disease severity (mild chronic gastritis, moderate chronic gastritis, and severe chronic gastritis)." (PMID 29391865, 2017).
chronic hepatitis (2 papers, 2021 to 2022). An active inflammatory process affecting the liver for more than six months. "To identify the role of IL-12, IL-18, IL-21, and AchE in chronic hepatitis HBV patients, we compared the levels in different serum ALT groups." (PMID 36383803, 2022). "In human HBV hepatitis, there are more IL-21-producing CD4+ T cells in acute hepatitis than in chronic hepatitis, and the number is positively correlated with the number of HBV-specific CD8+ T cells." (PMID 34502427, 2021). "In this way, for HBV infection, IL-21 works to eliminate HBV in acute infection, but it is also involved in the transition from chronic hepatitis to liver cirrhosis, so great care should be taken when using IL-21 as a therapeutic agent." (PMID 34502427, 2021).
chronic hepatitis C (2 papers, 2018 to 2022). "Recently, IL-21 was suggested as a predictor of sustained virologic response (SVR) in chronic hepatitis C because high levels of IL-21 were clearly linked with achievement of SVR." (PMID 30223493, 2018). "Recently, it was shown that patients with sustained virologic response (SVR) had higher pretreatment serum IL-21 levels, which suggests that the pretreatment serum IL-21 level could be a biomarker to predict SVR in chronic hepatitis C patients." (PMID 30223493, 2018).
Coma (2 papers, 2023 to 2025). The complete absence of wakefulness and consciousness, which is evident through a lack of response to any form of external stimuli. "Similarly, CXCL10, IL-22, IL-21, and IL-1α were negatively associated with the need for mechanical ventilation and coma duration." (PMID 41219650, 2025).
cutaneous leishmaniasis (2 papers, 2014 to 2018). Leishmaniasis affecting the skin. "Furthermore, the formation of a functional germinal center and IL-21 production were associated with lesion resolution in a model of cutaneous leishmaniasis." (PMID 24763747, 2014). "Moreover, skin lesions of patients affected by cutaneous leishmaniasis caused by L. (V.)braziliensis showed a stronger correlation between IL-10 expression and proinflammatory cytokines such as IFN-γ, IL-27, and IL-21, rather than with FoxP3+ cells." (PMID 29743809, 2018).
dermatomyositis (2 papers, 2024 to 2025). Dermatomyositis (DM) is a type of idiopathic inflammatory myopathy characterized by evocative skin lesions and symmetrical proximal muscle weakness. "Specifically, expression of the IL21 gene was found to be upregulated in patients with PM and dermatomyositis." (PMID 39746095, 2025). "In addition, another study has identified a significant upregulation of IL21, a prominent cytokine primarily synthesized by Tfh cells, within the context of dermatomyositis, thereby further implicating their pivotal role in the pathogenesis of DM." (PMID 38389573, 2024).
dry eye (2 papers, 2022 to 2024). "Increases of IFN-γ, IL-2, IL-4, IL-5, IL-13 or IL-β1 in SAC; TSLP in both PAC and SAC; and IL-17, IL-21 and IL-22 in dry eyes have been observed in different studies." (PMID 35935953, 2022). "Also, HL036, a molecularly engineered TNF Receptor 1 fragment, improves corneal staining, reduces ocular discomfort, suppresses lacrimal inflammation, decreases corneal inflammation, and improves goblet cell counts by suppressing IFN-γ, IL-21, and IL-6 in a dry eye-induced C57BL/6 mice model." (PMID 38399390, 2024).
follicular lymphoma (2 papers, 2017 to 2024). Follicular lymphoma is a form of non-Hodgkin lymphoma characterized by a proliferation of B cells whose nodular structure of follicular architecture is preserved. "The HS5-CD40L-IL4 ± IL21 co-cultures might be useful to induce proliferation in other ”mature” B cell malignancies such as follicular lymphoma (FL), marginal zone lymphoma (MZL) or DLBCL that depend on T-cell factors." (PMID 38877102, 2024).
genital warts (2 papers, 2022 to 2025). "Low serum levels of IL-21 and IL-33 can increase the risk of acquiring HPV infection and developing genital warts." (PMID 40142865, 2025). "IL-21 may contribute to both initial immune responses and control of HPV-associated genital warts." (PMID 35656032, 2022).
head and neck squamous cell carcinoma (2 papers, 2021 to 2023). A squamous cell carcinoma that arises from any of the following anatomic sites: lip and oral cavity, nasal cavity, paranasal sinuses, pharynx, larynx, and salivary glands. "Here, we demonstrated that IL-21-polarized inflammation was enriched in the tumor microenvironment in head and neck squamous cell carcinoma (HNSCC) and that IL-21 could promote PD-L1-induced Treg generation in a PD-1-dependent manner." (PMID 34026621, 2021).
Headache (2 papers, 2021 to 2026). Cephalgia, or pain sensed in various parts of the head, not confined to the area of distribution of any nerve. "Regarding the central tendency measures, in the comparison of the crude median values of cytokines, we observed that patients with headache had higher median values of GROa, IFN-gamma, IL-10, IL-13, IL-15, IL-17a, IL-21, IL-22, IL-27 and IL-6." (PMID 34088273, 2021).
immune thrombocytopenia (2 papers, 2017 to 2021). "In the peripheral blood of children with immune thrombocytopenia (ITP), the frequency of TFR cells in the peripheral blood decreased, the frequency of TFH cells increased, the level of plasma IL-2 decreased, and the level of plasma IL-21 increased." (PMID 29312316, 2017).
interstitial lung disease (2 papers, 2022 to 2023). A diverse group of lung diseases that affect the lung parenchyma. "IL-23 is also elevated in SSc, and Th17-related cytokines (IL-17, IL-21, and IL-23) are associated with interstitial lung disease (ILD) and with its severity in SSc patients." (PMID 36614095, 2022). "SSc patients had higher serum levels of both IL-4 and IL-21 compared to HCs, and the serum levels of these cytokines were correlated with a reduction in the diffusion lung capacity for carbon monoxide (DLco) and the radiological extension of interstitial lung disease (ILD) in SSc patients." (PMID 37763102, 2023).
intestinal inflammation (2 papers, 2016 to 2023). "In mammals, IL-21 plays key roles in the development of inflammatory diseases and intestinal inflammation and significantly ameliorates DSS-induced intestinal inflammation." (PMID 37759501, 2023).
intestinal tumor (2 papers, 2022 to 2024). "The reduction in IL-21 expression was reminiscent of an earlier study, which documented that IL-21 deficiency correlates with an enhancement of the Th17 axis in sporadic intestinal tumor genesis." (PMID 38954024, 2024). "However, another study proved that IL-21 stimulated a cytotoxic anti-tumor response in CRC, and the lack of IL-21 promoted intestinal tumor formation through the dysregulation of the Th1/Th17 axis." (PMID 36275766, 2022).
Large vessel vasculitis (2 papers, 2013 to 2024). A type of vasculitis (inflammation of blood vessel walls) affecting large arteries such as the aorta and branches of the aorta. "Data indicated that inappropriate synthesis of IL-21 triggered rapid development of a large vessel vasculitis." (PMID 38928233, 2024). "In their study, mice deficient in interferon regulatory factor-4, a protein that inhibits IL-17A production, rapidly developed large-vessel vasculitis and showed increased IL-21 synthesis in addition to increased IL-17A production." (PMID 23799890, 2013).
leprosy (2 papers, 2013 to 2016). Leprosy is a chronic infectious disease affecting primarily the skin and peripheral nervous system. "Within the leprosy spectrum the more resistant paucibacillary form of tuberculoid leprosy had higher IL-17 associated cytokines IL-21, IL-22 and the transcription factor RORC." (PMID 23936569, 2013). "In conclusion, Th17 cells with intracellular IL-17A, F are increased in both types of leprosy reactions whereas CD4+IL-21+ cells were higher only in ENL reactions patients." (PMID 27035913, 2016). "Both types of reactions are associated with significant increase of Th17 cells and associated cytokines IL-17A, IL-17F, IL-21, IL-23 and chemokines CCL20, CCL22 as compared to matching stable forms of leprosy." (PMID 27035913, 2016). "It is of interest that the same subjects also showed higher percentage of IL-21+ cells in both types of leprosy." (PMID 23936569, 2013). "Moreover, within the leprosy groups IL-21(p<0.002) and IL-22 (p<0.002) were significantly higher in BT as compared to LL type." (PMID 23936569, 2013). "Skin biopsies did not reveal differences in the leprosy types and only IL-21 showed significantly higher expression in dermal lesions of BT leprosy as compared to normal skin samples (p<0.001)." (PMID 23936569, 2013). "Unlike IL-17, IL-21 was present in both CD4+ and CD8+ T cells in the two clinical types of leprosy." (PMID 23936569, 2013).
leptospirosis (2 papers, 2018 to 2020). A contagious bacterial infection caused by spirochetes of the genus Leptospira. "Elevation of IL-17A together with the significant elevation of IL-21 and IL-23 suggests a possible involvement of Th17 cells in the immunopathogenesis of leptospirosis." (PMID 30123395, 2018). "The significant elevation of IL-23, IL-21 and elevation of IL-17 observed in this study suggest a possible role of Th17 cells in the inflammatory response among patients with leptospirosis." (PMID 30123395, 2018). "Interestingly, there was a significant elevation in IL-21 and IL-23 among leptospirosis patients with renal failure." (PMID 30123395, 2018). "The mean concentrations of IL-21, IL-23, and TNF-α among the leptospirosis patients were 14.69 pg/ml ± 13.1, 54.06 pg/ml ± 28.1, and 700 pg/ml ± 619, respectively." (PMID 30123395, 2018). "The serum cytokine levels of IL-10, IL-17A, IL-21, IL-23, and TNF-α were investigated in 57 patients with leptospirosis and 12 healthy controls using a commercially available ELISA kit (Mabtech, Sweden)." (PMID 30123395, 2018). "According to the present study, IL-21, IL-23, and TNF-α levels were significantly elevated among leptospirosis patients compared to the healthy controls." (PMID 30123395, 2018). "Elevation of serum IL-10 and IL-17A levels and significant elevation of serum IL-21 (p=0.002), IL-23 (p=0.002), and TNF-α (p=0.039) were observed among leptospirosis patients compared to the healthy control group." (PMID 30123395, 2018). "Among the five cytokines tested, IL-21 (p=0.002), IL-23 (p=0.002), and TNF-α (p=0.003) were significantly elevated among leptospirosis patients compared to the healthy controls." (PMID 30123395, 2018). "Moreover, IL-21, IL-23, and TNF-α levels were significantly increased among leptospirosis patients with liver insufficiency." (PMID 30123395, 2018). "However, though not conclusive, the finding that IL-21 and IL-23, which are involved in the Th17 pathway, were significantly elevated together with high levels of IL-17 in this study suggests the possible involvement of TH17 pathway in the immune response in leptospirosis." (PMID 30123395, 2018).
lung disease (2 papers, 2015 to 2024). "Our studies establish a novel crosstalk between IL-21 and IL-1β, and this crosstalk may contribute to the uncontrolled inflammatory responses during PVM-induced lung disease." (PMID 26269257, 2015).